PDGFRB (platelet derived growth factor receptor beta)
Diseases named in the same sentence as PDGFRB in open-access papers (continued):
Sharing a sentence is not in itself a finding about the gene and the disease.
tumor (continued). "Importantly, the PDGFRβ aptamer (intravenous administration) potentiated the efficacy of the anti-PD-L1 antibody in inhibiting tumor growth and lung metastasis formation in a syngeneic 4T1 TNBC mouse model by acting on both tumor cells and immune populations." (PMID 36046085, 2021). "The tumours were analysed via flow cytometry for the simultaneous expression of six CAF markers: alpha smooth muscle actin (αSMA), fibroblast activation protein alpha (FAPα), platelet derived growth factor receptor alpha and beta (PDGFRα and PDGFRβ), CD26/DPP4 and podoplanin (PDPN)." (PMID 34016130, 2021). "Interestingly, a recent report evaluated PDGFRα, PDGFRβ and PDGF-CC expression of tumor and/or stromal cell in primary tumors (N = 489), synchronous lymph node metastases (N = 135) and asynchronous recurrences (N = 39) using immunohistochemistry in a prospectively maintained cohort of BC patients." (PMID 34885027, 2021). "In this context, additional CAF subtypes were identified: CAF-1 cells expressing FSP-1, which promote metastatic colonization of tumor cells through tenascin- and VEGF-mediated angiogenesis; and CAF-2 cells that are characterized by the presence of αSMA, neural/glial antigen 2 (NG2), and PDGFRβ." (PMID 33806802, 2021). "In contrast, tumor expression of PDGFRB did not influence BLCA patient prognosis." (PMID 34858395, 2021). "PDGFRb could simply be a marker for a functional fibroblast or vascular mural cell subset with distinct effects on tumor progression, and our study suggests that it may not correlate strongly with overall stroma." (PMID 33661437, 2021). "They further discovered that these FAP+/PDGFRβ+ cells participated in TGFβ secretion in GBM, which is consistent with previous studies showing that GBM-activated pericytes secrete high levels of immunosuppressive cytokines, including IL-10 and TGFβ, and promote tumor growth." (PMID 34068501, 2021). "Thus, it has been suggested that initial steps of the angiogenic process in BC development may be characterized by an increase in PDGFRβ+/NG2+ double positive cells, close to the perivascular niche of the tumor." (PMID 34885027, 2021). "Although tumor stromal fibroblasts in general may express α-SMA, FAP, vimentin, neuron-glial antigen-2 (NG2) chondroitin sulfate proteoglycan, PDGFRβ, prolyl 4-hydroxylase and FSP1; α-SMA and FAP can be used to discriminate myofibroblasts form fibroblasts in the tumor tissue." (PMID 34336660, 2021). "However, the anti-PDGFRβ-augmented tumor angiogenesis did not instigate accelerated tumor growth, suggesting the non-productive features of these vessels." (PMID 32709869, 2020). "Studies of mechanisms in vitro support that tumor cell-derived LOXL2 directly stimulated stromal fibroblast proliferation and activity by enhancing PDGF-AB-mediated signaling after modification of PDGFRβ, while having no proliferative effect on tumor cells themselves." (PMID 31086173, 2019). "However, supporting that several growth factor receptors can regulate the expression of CDCP1, not all CDCP1-positive specimens expressed PDGFRβ in the tumor cells." (PMID 29792166, 2018). "IHC staining for PDGFRβ expression in subcutaneous tumor tissue revealed high levels of PDGFRβ expression even in no-dox tumors, which may explain the only modest increase in the plus-dox condition." (PMID 29367463, 2018). "However, the tumor uptake of a radiobrominated compound was not high enough as an appropriate probe for PDGFRβ imaging, and further modification is still needed." (PMID 29991770, 2018). "Indeed, treatment of RipTag2 tumours with anti-PDGFRβ antibody reduces pericyte numbers and enlarges blood vessels but does not reduce tumour vascular density." (PMID 28289267, 2017). "However, illumination did not induce obvious cell death in PDGFRβ− LS174T tumor cells under the same conditions." (PMID 29182023, 2017).
tumor (continued). "Following expansion, flow cytometric analysis revealed the presence of PDGFRα (CD140a) and PDGFRβ (CD140b) on tumor-derived Lin-EpCAM-CD73+CD90+ mesenchymal cells and their normal counterparts, as well as human lung fibroblasts (HLFib) and bone marrow-derived MSCs (BM-MSC)." (PMID 28878242, 2017). "Moreover, the distribution profile of PDGFRβ is identical to that of NG2, whereas few α-SMA+ cells were observed in tumor tissues, indicating that among the mural cells of tumor blood vessels, PDGFRβ+ cells were predominantly pericytes, not smooth muscle cells." (PMID 29182023, 2017). "Moreover, cellular localization analysis demonstrated that FAM-labeled ZPDGFRβ affibody co-localized well with PDGFRβ and with NG2, suggesting that the ZPDGFRβ affibody was predominantly distributed on pericytes in the mural of tumor blood vessels." (PMID 29182023, 2017). "In line with a role of Notch3 in tumour associated endothelial cells, we observed an increase in CD31 and DLL4 expression in tumours from Notch3LacZ/LacZ mice, but no change in αSMA or PDGFRβ (Beta-type platelet-derived growth factor receptor), two pericyte markers." (PMID 28719575, 2017). "Moreover, PDGFRβ expression was restricted to stromal fibroblast components and Panc02 tumour cells in vitro have barely detectable levels of PDGFRβ expression, supporting the non-tumour cell expression of PDGFRβ." (PMID 27150562, 2016). "Subsequent immunostaining of OSCC specimens demonstrated that PDGFRβ was abundantly expressed in stromal fibroblasts of all tested cases (12/12), while it was absent in tumor cells, with greater specificity than other known markers such as alpha smooth muscle actin or podoplanin (3/11)." (PMID 27128408, 2016). "Accordingly, over-expression of ZEB2 and TWIST1 in surgical samples of both normal and tumor tissues can induce EMT, resulting in over-expression of representative EMT markers VIM, FN, and COLs and membrane signal transducers IL8, CXCL4, CCL5, CXCR4, PDGFRB, and TLR2." (PMID 21533028, 2011). "In contrast, combining TAK-779 treatment with PDGFRβ vaccine failed to considerably reduce the extent of tumor and carcinosis development compared to each treatment alone, again supporting the greatest potential of CCL5 inhibition compared to CCR5 antagonism in this CRC model." (PMID 22205974, 2011). "Correlations were also observed between PDGFRβ status in tumor stroma and non-malignant stroma." (PMID 20505768, 2010). "The cut-offs for tumor stromal PDGFRβ and non-malignant stromal PDGFRβ in the analyses was set to the third quartile, corresponding to 1.0 and 0.5 for tumour and non-malignant stromal PDGFRβ staining, i.e. high PDGFRβ immunoreactivity was ≥1.0 for tumour and ≥0.5 for non-malignant stroma." (PMID 20505768, 2010). "Similarly, high PDGFRβ expression in adjacent non-malignant tissue stroma correlated with large tumor size, advanced stage, high Gleason score and proliferation in non-malignant epithelium." (PMID 20505768, 2010). "Sorafenib hits tumor cells on multiple levels such as the Raf/MEK/ERK signalling pathway, as well as angiogenesis by targeting vascular endothelial growth factor receptors-1/-2/-3 (VEGFR-1/-2/-3) or platelet derived growth factor receptor beta (PDGFR-β) tyrosine kinases." (PMID 19558720, 2009). "However, the study is to a certain extent limited through the utilization of a TMA format, which, although two cores per patient are included, may not sufficiently reflect heterogenous PDGFRb expression throughout the tumor tissue." (PMID 33661437, 2021). "In addition, inside the tumor mass, we found PDGFRβ and CD13 double‐positive, nonperivascular pericyte‐like cells, origin of which is unknown." (PMID 32534480, 2020). "Thus, we analysed the ability of AsiC to affect tumour sphere formation in PDGFRβ-negative GSCs." (PMID 32486489, 2020).
tumor (continued). "Moreover, our analysis of tumor microenvironment both in our orthotopic tumors and in PTC clinical samples provides evidence that metastatic BRAFV600E-PTC with MCL1 and P16 copy number alterations are enriched with PDGFRB-positive stromal cells (i.e. pericyte)." (PMID 26636651, 2015). "In addition, regorafenib alone and in combination reduced phosphorylation of PDGFRB, which may also contribute to anti-tumor effects, however, without affecting AKT or ERK1/2 phosphorylation." (PMID 26599335, 2015). "However, sorafenib also inhibits several receptor tyrosine kinases that may be involved in tumor angiogenesis and progression, e.g., human and murine vascular endothelial growth factor receptor-2 (VEGFR-2), VEGFR-3, platelet-derived growth factor receptor-beta (PDGFR-β), Flt3, and c-KIT." (PMID 22347360, 2012). "While PDGFRβ-targeted perturbation in fibroblasts altered CRC cell proliferation and migration, we did not delineate downstream signaling pathways in tumor cells." (PMID 41601676, 2026). "Furthermore, in vivo studies are needed to map the PDGFRβ-centered PTM network in stromal cells and TME, to clarify its contribution to CRC progression, and to evaluate whether inhibiting these pathways—alone or in combination with immunotherapy—can improve tumor control." (PMID 41601676, 2026). "It is highly expressed in numerous fibroblasts within the stroma surrounding tumor islands in most OSCC cases, whereas no PDGFRβ expression has been detected in tumor cells." (PMID 39928309, 2025). "Regarding EFS, only tumor site (p=0.015) reached statistical significance while stage III-IV (p=0.05), c-Kit (p=0.16), VEGFR2 (0.29), PDGFRα (p=0.0.25) or PDGFRβ expression (p=0.8) failed to reach statistical significance." (PMID 39534097, 2024). "We also performed immunohistochemistry with an anti-PDGFRβ antibody and an anti-NG2 antibody (BVP markers) in PDX model YML16, and found that cells positive for both PDGFRβ and NG2 were surrounded by tumor cells in areas without obvious vascular structures." (PMID 38089883, 2023). "The qRT-PCR analysis of 20 pairs of BC and adjacent non-tumor tissues showed that the expression of PDGFRB, COMP, GREM1, and FRRS1 was higher in BC tissues than in non-tumor tissues." (PMID 36895470, 2023). "Furthermore, fibrogenic factors, including PDGFRβ, CXCR4, and TGFB1, which may be expressed by the stromal cells or the reprogrammed brain cells, can potentiate fibrosis in the metastasis brain environment which, in turn, contributes to increased angiogenesis and tumor growth." (PMID 36216799, 2022). "A similar interaction was also shown between PDGFRβ+/αSMA+ CAF-derived fibronectin and integrin-αv/β3 positive colon cancer cells, where absence of fibronectin completely abrogated tumor cell invasion." (PMID 36671452, 2022). "We utilized the pan-myeloid marker, IBA1; pan astrocyte (non-tumor) and tumor cell marker GFAP; endothelial cell marker (UAE-1-lectin); and stromal cell marker PDGFRβ." (PMID 36382105, 2022). "Treatment with the STAT5 SH2-domain inhibitor AC-4-130, results in a reduction in tumor growth in ALK+ ALCL, irrespective of PDGFRβ expression." (PMID 36045346, 2022). "We found that PDGFRβ, PKCα, FRA1, and VIM were readily detected in ER− and BRCA1 weak or non-detectable tumor cells, whereas these proteins were barely detectable in ER+ and BRCA1+ tumor cells." (PMID 33478572, 2021). "The predictive value of high intratumoral PDGFRβ and VEGFR2 protein expression was independent of other clinico-pathologic parameters such as tumor stage or histologic subtype." (PMID 29228656, 2017). "Analysis of the expression of CAF related proteins in metastatic tumor according to the metastasis site revealed no expression of PDGFRβ and NG2 in the tumor cells, and no expression of prolyl 4-hydroxylase in the stromal component." (PMID 26163388, 2015). "Single-cell suspensions of tumor tissue were gated for non-immune (CD45−), non-epithelial (Ep-CAM−) cells and detected as PDGFRβ+PDGFRα." (PMID 25280532, 2014).
tumor (continued). "When the tumor subtypes without a counterpart were analyzed via GSAA, we observed PDGFRB_STP co-expressed with aberrantly expressed MYC and STAT3 only in luminal A." (PMID 23516564, 2013). "The association of PDGFRβ primarily with the stroma, and not tumor cells, in both AGASACA and TC suggests that toceranib may be exerting much of its biologic activity through effects on the tumor stroma and blood supply, particularly in cases where SD is observed." (PMID 22630170, 2012). "Real-time quantitative RT-PCR analysis on sorted cell compartments from RIP-Tag2 tumors demonstrated Arf expression, as expected, in the tumor cell compartment, but not in endothelial cells (CD31+), immune cells (CD45+), or pericytes (Pdgfrβ+)." (PMID 20805995, 2010). "Moreover, analysis of paired tumor and normal tissue samples showed no significant differential expression of COL1A1, PDGFRB, and SPARC." (PMID 41040657, 2025). "Indeed, the few tumours and metastases that did not classify as CMS4 also had the lowest expression of PDGFRB." (PMID 36139509, 2022). "In the E0771 tumor model, no change in lung NF activity was observed, but CAFs in mice fed with a vitamin-D-supplemented diet (5000 IU) were activated as podoplanin, TNC, and PDGFRβ increased." (PMID 36230508, 2022). "Finally, co-staining for PDGFRβ and STAT5 indicated both factors are expressed in tumor cells and do not originate from different cell populations." (PMID 36045346, 2022). "OS cells (Saos–2 cell line) downregulate the expression of angiogenic factors, such as CD34, PDGFA, PDGFRA, PDGFRB, and VEGF, in human AD-MSCs when co-cultured, implying that MSCs cannot differentiate in vitro under the induction of tumor cells and do not support tumor angiogenesis in vivo." (PMID 34681692, 2021). "Both PDGFRα and -β are expressed by tumor cells of STS, yet expression of specifically PDGFRα is evaluated in this review as a monoclonal antibody against this receptor has been clinically tested in STS, while not against PDGFRβ." (PMID 33535618, 2021). "On average, αSMA, PDGFRβ and CD31 were not differently expressed between the tumor center (αSMA M = 0.122, SE = 0.019; PDGFRβ M = 0.152, SE = 0.034; CD31 M = 0.014, SE = 0.005) and the invasive part (αSMA M = 0.092, SE = 0.014; PDGFRβ M = 0.134, SE = 0.026; CD31 M = 0.010, SE = 0.002; P > 0.05)." (PMID 30922247, 2019). "Only 2 tumours had high expression of PDGFRβ and PDGF-CC in combination with absent or low expression of PDGFRα (in both stromal and tumour cells), whereas 42 tumours had high expression of PDGFRα (in stromal and/or tumour cells) and PDGF-CC in combination with low PDGFRβ." (PMID 29380207, 2018). "Regarding tumor nests, 57% (37/65) of cases were CDCP1-positive, 45% (29/65) was PDGFRβ-positive, 32% (21/65) was positive for CDCP1 and PDGFRβ (double-positive), and 31% (20/65) was negative for CDCP1 and PDGFRβ (double-negative)." (PMID 29792166, 2018). "Imatinib and nilotinib treatment resulting in enhanced invasion through increased p130Cas and FAK signalling could lead to selection of tumour cells with increased motility independent of c-ABL and PDGFRβ signalling pathways." (PMID 27293031, 2016). "In the first example of supervised GSAA, we had demonstrated that the PDGFRB signal transduction pathway (PDGFRB_STP) was differentially regulated by STAT3 and MYC in non-tumor and tumor components, which was supported by our previous studies (and unpublished data of ours)." (PMID 23516564, 2013). "Therefore, we analysed PDGFRB mRNA and protein levels in the primary CRC tumours of the TCGA cohort (n = 582; without known peritoneal involvement); in primary tumours with peritoneal involvement (n = 35 regions from 12 patients); and in paired peritoneal metastases (n = 59)." (PMID 36139509, 2022).
cancer (555 papers, 2006 to 2026). A tumor composed of atypical neoplastic, often pleomorphic cells that invade other tissues. "Numerous studies indicate that a higher abundance of PDGFRβ-positive cancer-associated fibroblasts (CAFs) is associated with worse outcomes." (PMID 41601676, 2026). "In our caseload, PDGFRβ expression was observed in CAFs and cancer-associated blood vessels of most primary tumors and lymph node metastases, but not in the stroma." (PMID 41472102, 2025). "Our interpretation of the Kaplan–Meier analysis revealed that PDGFRB is a risk factor in cancer patients." (PMID 40128057, 2025). "In this study, we investigated the pan-cancer expression of PDGFRB and its association with prognosis in cancer patients." (PMID 40128057, 2025). "Overall, our findings demonstrate that these small drug-like compounds can be beneficial tools in studying the properties of PDGFRβ and can play a crucial role in the therapeutic development of cancers and other associated diseases." (PMID 39473823, 2024). "Changes in the expression of miRNAs associated with cancer and hepatotoxicity were observed in dMASH of PDGFRβ KO mice." (PMID 39394459, 2024). "PDGFRB upregulation has been linked to poor outcome, treatment resistance, and metastasis in several cancers." (PMID 35406617, 2022). "Kinases that were rarely mutated, including MET, PIK3CB, and PDGFRA/PDGFRB, were found to be substantially overexpressed at the protein level in the same cancer types." (PMID 34552204, 2021). "Many fibrotic diseases and malignant tumors are associated with platelet-derived growth factor receptor beta (PDGFRβ) overexpression and disproportionate signaling, making this receptor attractive for molecular targeting and imaging approaches." (PMID 31652624, 2019). "In an additional follow-up study, it was observed that the levels of urinary PDGFRB in subjects with relapse were significantly higher than those without recurrence, and these were also correlated to the risk of 3-year cancer recurrence." (PMID 24801713, 2014). "PDGFRB is a cancer gene closely associated with prognosis and immunity in cancer patients, and it may serve as an immune checkpoint." (PMID 40128057, 2025). "PDGFRB has been reported to be upregulated in cancer‐associated fibroblasts of CCA." (PMID 38877653, 2024). "The elevated expression of PDGFRβ is linked with various diseases, including cancer." (PMID 39473823, 2024). "In particular, Cancer Associated Fibroblasts (CAFs) show a strong PDGFRB expression." (PMID 36139509, 2022). "Interestingly, cancer-associated fibroblasts (CAFs) promote DNM3OS expression in a PDGFβ/PDGFRβ/FOXO1 signaling pathway-dependent manner in ESCC, resulting in enhancing radioresistance." (PMID 36294743, 2022). "Furthermore, we have recently shown that integrin α11 associates to PDGFRβ in cancer associated fibroblasts and activates its JNK downstream signaling." (PMID 33014790, 2020). "Module 5 contains known EMT inducers ZEB1, SNAI2, and TCF4 (E2.2), as well as multiple other genes known to be important in focal adhesion, extracellular matrix interaction, extracellular matrix organization, and markers of cancer-associated fibroblasts (PDGFRB, PDGFRA)." (PMID 27287041, 2016). "Moreover, PDGFRB is strongly associated with the prognosis of cancer patients." (PMID 40128057, 2025). "Classical genes associated with an activated status of fibroblasts (FAP, PDGFRβ) were higher in normal adjacent tissues compared with normal tissues from healthy patients whereas AR levels that work as transcriptional repressors of cancer-associated fibroblast activation were lower." (PMID 35740605, 2022). "Upon targeting PDGFRβ on cancer cells, the aptamer-receptor interaction outcompetes Cy3-Gint4.T's binding to BPNSs, triggering its release and subsequent fluorescence restoration." (PMID 41884335, 2026).